ANK3 (ankyrin 3)
Diseases named in the same sentence as ANK3 in open-access papers (continued):
Sharing a sentence is not in itself a finding about the gene and the disease.
schizophrenia (49 papers, 2011 to 2025). A major psychotic disorder characterized by abnormalities in the perception or expression of reality. "Our study specifically focused on ANK3 mRNA expression as the gene has been found to be associated with both BD and schizophrenia in large GWAS14,16, and studies have also shown that ANK3 is influenced by early trauma experiences." (PMID 37620394, 2023). "The minor allele of rs958852 in ANK3 was associated with a 0.75-fold reduction in schizophrenia risk in an allelic model." (PMID 27811378, 2016). "In our study, we conducted a case-control study in a northern Chinese Han population of 499 schizophrenia patients and 500 controls to investigate the effect of variant genotypes of 13 SNPs in ANK3 on schizophrenia risk." (PMID 27811378, 2016). "We found that genotype “TA” of rs958852 in ANK3 was associated with a 0.68-fold lower risk of schizophrenia than genotype “AA” at the 5% level (95%CI 0.48–0.97; p = 0.031)." (PMID 27811378, 2016). "In sum, we confirmed a positive association between ANK3 and schizophrenia and also demonstrated that four ANK3 variants (rs10994336, rs10994338, rs4948418 and rs958852) are associated with schizophrenia in a northern Chinese Han population." (PMID 27811378, 2016). "Four susceptibility loci from ANK3 (rs10994336, rs10994338, rs4948418 and rs958852) were significantly associated with schizophrenia risk in a northern Chinese Han population for the first time." (PMID 27811378, 2016). "We also found that the “TTC” haplotype of ANK3 is associated with a 0.73-fold reduction in the risk of schizophrenia." (PMID 27811378, 2016). "In this case-control study, we investigated associations between genetic variations in ANK3 and schizophrenia risk in a relatively large sample of individuals." (PMID 27811378, 2016). "We attempt to replicate genetic association findings of ANK3 as a possible common risk factor for schizophrenia and affective disorders in a case control study of > 2000 subjects of German descent." (PMID 21702894, 2011). "An association between ANK3 and schizophrenia (albeit with a different risk marker in the first intron of ANK3 on 10q21) has already been reported underlying the importance of this gene for psychotic disorders." (PMID 21304963, 2011). "In addition, haplotype “TTC” of ANK3 was associated with a 0.73-fold reduced schizophrenia risk (95%CI: 0.54–0.99; p = 0.044)." (PMID 27811378, 2016). "In addition, an association between ANK3 and schizophrenia has been detected in several different ethnic groups." (PMID 27811378, 2016). "Furthermore, an ANK3 risk polymorphism is associated with decreased ANK3 gene expression, which is consistent with ANK3 gene expression downregulation in schizophrenia and neurocognitive and neuroimaging abnormalities." (PMID 24478629, 2014). "Another SNP in ANK3 (rs10761482) was associated with schizophrenia in a large European sample." (PMID 21702894, 2011). "Subsequent studies found a genetic marker at ANK3 to be associated with schizophrenia as well." (PMID 21702894, 2011). "In addition, ANK3, which overlapped with MIs in only East Asians, is reportedly a risk factor for schizophrenia, a chronic and severe mental disorder, in Han Chinese, which may explain the existence of MIs in ANK3 only in East Asians." (PMID 32929667, 2020). "In addition, ANK3 expression is reported to be lower in superior temporal gyrus of schizophrenia subjects, suggesting that ANK3 downregulation may underlie psychopathology." (PMID 23025490, 2012). "Intriguingly, transgenic expression of HERV-W ENV also led to impaired expression of several other genes that are implicated as genetic risk factors of schizophrenia and ASD, including Cacna1g, Ank3, Shank1, and Shank3." (PMID 40102613, 2025). "In the future, ANK3-ZNF804A interaction analysis should be investigated in other psychiatric disorders, such as bipolar disorder and schizophrenia, which have been found to be highly correlated with the ANK3 or ZNF804A gene." (PMID 38702695, 2024).
schizophrenia (continued). "While ZDHHC8 has not been yet associated with BD, it has been related to schizophrenia and epilepsy overlapping with ANK3." (PMID 36969554, 2023). "All four family members were either homozygous or heterozygous for the bipolar risk genotypes in the SYNE1, ANK3, CACNA1C, ODZ4 (TNM4) and ZNF804A genes, of which ZNF804A is also a schizophrenia risk allele." (PMID 32377792, 2020). "Second, our study lacks biological function experiments, which will be crucial for elucidating the role of ANK3 in schizophrenia." (PMID 27811378, 2016). "Several studies have reported that ANK3 plays an important role in the pathogenesis of schizophrenia." (PMID 27811378, 2016). "Further evidence will be needed to confirm this interaction in a wider population, and to determine the role of ANK3 in the development of schizophrenia." (PMID 27811378, 2016). "In addition to including members of the Set1-like H3K4 methyltransferase family (Kmt2a, Kmt2b, Kmt2c, and Kmt2d), these modules also encompassed rare variant genes associated with schizophrenia and ASD (Setd1a, Cacna1g, Ank3, Shank1, and Shank3)." (PMID 40102613, 2025). "Among them, MIR137, a micro-RNA, which is a regulator of neuronal development, showed the strongest association in schizophrenia (p-value = 1.6 × 10−11), and three more loci (CACNA1C, ANK3, and ITIH3-ITIH4) were significantly associated with both BD and schizophrenia." (PMID 34502224, 2021). "ANK3 overlapped with both positive psychotic experiences (visual hallucinations) and schizophrenia." (PMID 32152294, 2020). "For example, ANK3 has been associated with mental retardation, SLC45A1 with intellectual developmental disorder, and CHI3L1 with schizophrenia, suggesting that differential methylation data may help reveal novel genetic variations that associate with AD." (PMID 32539856, 2020). "It is anticipated that future studies will clarify the precise contribution of ANK3 to schizophrenia, which may offer a new strategies for the prevention and treatment of schizophrenia." (PMID 27811378, 2016). "The associations between ANK3 polymorphisms and schizophrenia risk have not been investigated in the northern Chinese Han population." (PMID 27811378, 2016). "Among the genes implicated in schizophrenia, susceptibility variants linked to genes affecting GABAergic transmission (GABA B receptor components GABBR1 and GABBR2, and loci linked to proteins that mediate GABA receptor turnover, such as ankyrin-G (ANK3)) were reported." (PMID 36979236, 2023). "Our findings suggest ANK3 may play an important role in schizophrenia." (PMID 27811378, 2016). "Several of these genomic markers are shared between BD and schizophrenia such as CACNA1C, CACNB2, NCAN, TRANK1, ITIH3-ITIH4, and ANK3." (PMID 34502224, 2021). "While the function of ANK2 in brain has not been as well researched as ANK3, ANK2 is a schizophrenia-related eQTL gene." (PMID 35886854, 2022). "A recently study demonstrated that several NOR genes and proteins, including ANK3, NFASC, NRCAM, CNTN2, and SCN8A are affected in schizophrenia." (PMID 24478629, 2014).
autism (13 papers, 2013 to 2025). Persistent deficits in social interaction and communication and interaction as well as a markedly restricted repertoire of activity and interest as well as repetitive patterns of behavior. "In the original publication published five years ago, we detected 59 candidate coding variants which might increase susceptibility to autism, and further identified ANK3 as the most likely candidate gene by manual examination." (PMID 30591030, 2018). "More recently, missense mutations in ANK3 were identified in four out of 67 patients with ASDs in an exome and candidate gene sequencing study, and have been identified in another study that sequenced balanced chromosomal abnormalities in patients with autism or related neurodevelopmental disorders." (PMID 23597238, 2013). "Similarly, the correlation between Ank1 and FRmax is intriguing because Ank1, an isoform of the autism gene Ank3, helps coordinate the localization of Nav subunits to the nodes of Ranvier." (PMID 29069078, 2017). "Additionally, we observed an enrichment (FDR = 0.015) for candidate autism genes, including FOXP1, CUL7, ANK3, and EP300, among the differentially expressed genes." (PMID 34657631, 2021).
autism spectrum disorder (11 papers, 2017 to 2025). A spectrum of developmental disorders that includes autism, and Asperger syndrome. "Autism spectrum disorder has been associated with heterozygous missense variants in ANK3, whereas a more severe neurodevelopmental phenotype is caused by isoform-dependent, autosomal-dominant, or autosomal-recessive loss-of-function variants." (PMID 34218362, 2021). "ANK3 is associated with both autosomal dominant and recessive neurodevelopmental disorders, including intellectual disability and autism spectrum disorder." (PMID 34867351, 2021). "The genetic variation of Ank3 is closely related to neurodevelopmental diseases such as autism spectrum disorder and intellectual disability." (PMID 37284462, 2023).
epilepsy (11 papers, 2011 to 2025). A brain disorder characterized by episodes of abnormally increased neuronal discharge resulting in transient episodes of sensory or motor neurological dysfunction, or psychic dysfunction. "The interactions between OTUD7A and Ankyrin-G (Ank3) and Ankyrin-B (Ank2) were disrupted by an epilepsy-associated OTUD7A L233F variant." (PMID 36604605, 2023). "Our results identify a novel EEG biomarker associating Ank3 genetic variation with BD and epilepsy and suggest modulation of gamma oscillations as a potential therapeutic target." (PMID 38123552, 2023). "The OTUD7A protein–protein interaction network included synaptic, axonal, and cytoskeletal proteins and was enriched for ASD and epilepsy risk genes (Ank3, Ank2, SPTAN1, SPTBN1)." (PMID 36604605, 2023). "Previous studies showed that deletion of Ank3-1b, a BD-associated variant of Ank3 in mice leads to increased firing threshold and diminished action potential dynamic range of parvalbumin (PV) interneurons and absence epilepsy, thus providing a biological mechanism linking epilepsy and BD." (PMID 38123552, 2023). "Previous characterization of these mice showed that Ank3-1bKO/KO mice have premature mortality rates, and meet the criteria for sudden death in epilepsy (SUDEP), so we also looked at seizure activity during REM and NREM sleep." (PMID 38123552, 2023). "The ankyrin 3 gene (Ank3) regulates neuronal circuit activity and abnormalities in the function of one of the products of Ank3, a voltage-gated sodium channel, leads to excessive firing in circuits which are involved in emotions, memory, and epilepsy." (PMID 35619621, 2022). "Haploinsufficiency and polymorphisms of ANK3 and SCN2A in patients with ASD and epilepsy imply that AIS dysfunction is involved in the comorbidity of these diseases." (PMID 32641624, 2020). "Similarly, Ank3-exon1b knockout (Ank3-1b KO) mice, a model relevant to epilepsy, also exhibited a higher prevalence of seizures during REM sleep, and Nlgn2 KO mice also showed abnormal EEG events that predominated during wakefulness and REM sleep." (PMID 41408339, 2025).
depression (10 papers, 2011 to 2025). "Eight SNPs were identified as associated with depressive disorder and belonged to the ANK3, BDNF, CACNA1C, and GRID1 genotypes, with the majority belonging to the ANK3 and CACNA1C genotypes." (PMID 38012695, 2023). "Eight SNPs were associated with depressive disorder, namely rs142101917, rs191244436, and rs541490076 of the ANK3 genotype; rs193069165 of the BDNF genotype; rs116938681, rs188470158, and rs565998563 of the CACNA1C genotype; and rs558147168 of the GRID1 genotype." (PMID 38012695, 2023). "According to the generalized estimating equation analysis results, 8 single nucleotide polymorphisms (SNPs) belonging to the ANK3, BDNF, CACNA1C, and GRID1 genotypes were significantly correlated with depressive disorder (P < .001), with the majority belonging to the ANK3 and CACNA1C." (PMID 38012695, 2023). "These genes include CHD7, ADCY3, ANK3, NWD1, CNTNAP2 and TSNAX-DISC1, each of which has been carefully considered and contrasted as no previous link between neural disorders or psychiatric conditions, including depression, has been made for risk preference." (PMID 34696705, 2022).
Anxiety (9 papers, 2014 to 2025). Intense feelings of nervousness, tension, or panic often arise in response to interpersonal stresses. "Specifically, in ZNF804A rs7525957 CC homozygote carriers, ANK3 rs10994336 T allele carriers (M = 31.84, SD = 9.57) exhibit higher anxiety than CC homozygote carriers (M = 35.72, SD = 10.14) (t = 2.72, p = 0.007)." (PMID 38702695, 2024). "In ZNF804A rs7525957 CC homozygote carriers, ANK3 rs10994336 T allele carriers exhibit higher anxiety than CC homozygote carriers (t = 2.78, p = 0.006)." (PMID 38702695, 2024). "Therefore, the moderating effect of ZNF804A rs7525957 on anxiety and aggression appears only in ANK3 rs10994336 T allele variation." (PMID 38702695, 2024). "Finally, we assessed the moderating influence of candidate genes whose level of methylation is associated with the Nr3c1 genotype on anxiety-like behavior: Ank3, Avp, Avpr1a, Avpr1b, Bdnf, Cacna1c, Cyp11b1, Cyp11b2, Fkbp5, Hsd11b1, Igf2, Morc1, Nr3c1, Oxt, Oxtr, Pclo, Slc6a4." (PMID 30655507, 2019). "Contrasting anxiety phenotypes have also been found in mice haploinsufficient for the SZ/BD risk gene CACNA1c and in mice heterozygous for the BD associated gene Ank3 showing altered behavior in elevated plus maze and light-dark preference but not in the open field test." (PMID 25340473, 2014). "ANK3, ZNF804A, and the interaction term ANK3 x ZNF804A were entered as predictors of anxiety and aggression." (PMID 38702695, 2024). "The lowest anxiety and aggression scores were observed in individuals with the ANK3 rs10994336 CC homozygote and ZNF804A rs7525957 CC homozygote genotype." (PMID 38702695, 2024). "Individuals carrying the ANK3 rs10994336 T allele and ZNF804A rs7525957 CC homozygote genotype had the highest anxiety and aggression scores." (PMID 38702695, 2024). "This study primarily focuses on exploring the single and interaction effects of single-nucleotide polymorphisms in the ANK3 and ZNF804A genes on anxiety and aggression severity manifested in AWS." (PMID 38702695, 2024). "For example, one study showed that Ank3-1bKO/+ mice model aspects of BD such as shifts from manic-like features, including reduced anxiety and increased motivation for reward, to depressive-like features after chronic stress that were attenuated by lithium." (PMID 38123552, 2023). "Similar to the mice with DG-specific decrease of Ank3 expression, Ank3-1b+/− mice displayed reduced anxiety-like behavior in the EPM, light-dark transition, and novelty-suppressed feeding tasks." (PMID 29628501, 2018). "Similar behavioural alterations of reduced anxiety and increased motivation for reward were also exhibited by Ank3+/− heterozygous mice compared with wild-type Ank3+/+ mice." (PMID 24716743, 2014). "In another animal model, RNA interference of Ank3 in the hippocampus dentate gyrus induced a reduction of anxiety-related behaviours and increased activity during the light phase, which were attenuated by chronic treatment with the mood stabilizer, lithium." (PMID 24716743, 2014). "Therefore, the objective of this study was to examine the effects of ANK3 and ZNF804A variants, as well as their interaction, on the anxiety and aggression severity of AWS in patients diagnosed with AUD." (PMID 38702695, 2024). "The interaction of ANK3 and ZNF804A accounted for a significant portion of the variance in anxiety (β = -0.20, t = -2.25, p = 0.025) and aggression (|β|s > 0.23, |t|s > 2.59, p < 0.010)." (PMID 38702695, 2024). "Lastly, a series of hierarchical regression analyses was conducted to confirm the interaction effects of ANK3 and ZNF804A on anxiety and aggression." (PMID 38702695, 2024). "Two-way ANOVA further demonstrated a significant interaction effect between ANK3 rs10994336 and ZNF804A rs7597593 on anxiety, physical aggression, verbal aggression, anger, and hostility." (PMID 38702695, 2024).
Anxiety (continued). "For ANK3 rs10994336 CC homozygote carriers, ZNF804A rs7525957 T allele carriers do not show lower anxiety and aggression compared to CC homozygote carriers." (PMID 38702695, 2024). "However, MANOVA and a series of interaction analyses revealed that ZNF804A rs7597593 could regulate the effect of ANK3 rs10994336 on AWS-related mood and behavior, including anxiety, physical and verbal aggression, anger, and hostility." (PMID 38702695, 2024).
breast carcinoma (8 papers, 2006 to 2025). "Moreover, studies have demonstrated that ANK3 is associated with prostate cancer and breast cancer by regulating the stability of AR." (PMID 35646694, 2022). "There are few reports on ANK3 in cancer, and one showed that ANK3 can be used as a prognostic factor for two primary histologic subtypes of cutaneous melanoma and may be associated with breast cancer prognosis by regulating the androgen receptor signaling pathway." (PMID 35988113, 2022). "In contrast, Kurozumi reported that breast cancer cells showed uniform ANK3 immunoreactivity primarily in the cytoplasm." (PMID 35646694, 2022). "A breast cancer risk model consisting of 5 AS events was constructed in our study, which was risk score = (TTC39C|44853|AT*− 2.67) + (HSPBP1|52052|AP*− 4.28) + (MAZ|35942|ES*2.34) + (ANK3|11845|AP*1.18) + (ZC3HAV1|81940|AT*1.59)." (PMID 35988113, 2022). "It is of note that other members of the ankyrin family, namely ANK1 and ANK3, have been shown to be overexpressed in multiple human cancers including breast cancer, while ANK2 overexpression has been shown in pancreatic cancer where it contributed to the malignant phenotype." (PMID 33218035, 2020). "In our breast cancer study we found ankyrin 3 expression levels to be up-regulated compared to normal tissue, while here we report ankyrin 3 levels to be down-regulated (approximately 1.6 fold) [expression values 350.02 vs. 224.48], in BCC compared to normal tissue." (PMID 17173689, 2006). "In this study, various breast cancer cell lines and endometrial cells were used to analyze different expression levels of multiple target antigens (EGFR, FOLR1, HER2, EpCAM, NG2, ANK3 and CTNNB1) through flow cytometry and fluorescence microscopy." (PMID 40422194, 2025).
Intellectual disability (7 papers, 2017 to 2023). "All four presented with intellectual disability and speech delay, similar to two previously reported cases bearing similar ANK3 loss-of-function variants." (PMID 34218362, 2021). "In 2017, we reported the first individual harboring a heterozygous de novo nonsense variant which affected all three ANK3 isoforms who presented with mild intellectual disability, autistic, and behavioral abnormalities." (PMID 34218362, 2021).
melanoma (6 papers, 2018 to 2025). A malignant, usually aggressive tumor composed of atypical, neoplastic melanocytes. "The top 10 mutated genes in melanoma were TTN (72%), MUC16 (67%), DNAH5 (49%), PCLO (44%), LRP1B (38%), ANK3 (32%), DNAH7 (32%), ADGRV1 (35%), RP1 (33%), and BRAF (51%)." (PMID 33758620, 2021). "The top 10 mutated genes in 467 melanoma patients are TTN (72%), MUC16 (67%), BRAF (51%), DNAH5 (49%), PCLO (44%), LRP1B (38%), ADGRV1 (35%), RP1 (33%), ANK3 (32%), DNAH7 (32%)." (PMID 33072607, 2020). "ANK3, a negative regulator of cell invasion, was one of the most highly expressed genes in NTF2 high dox + cells and VGP melanoma." (PMID 34880267, 2021).